AADACL3 (arylacetamide deacetylase like 3)
Synonyms: OTTHUMG00000001887
Tractability: No criterion of Open Targets' tractability assessment is met for any kind of drug.
Gene: Protein-coding gene on chromosome 1 (12,716,110 to 12,728,760, forward strand). Ensembl gene ENSG00000188984.
Gene Ontology:
Molecular function: carboxylic ester hydrolase activity; hydrolase activity
Cellular component: membrane
Genetic constraint (gnomAD): Loss-of-function variants: 10 observed, 13.57 expected, observed/expected ratio (o/e) 0.74, 90% interval 0.45 to 1.25. The upper end of that interval is the gene's LOEUF score, 1.25, which puts it in group 5 of 6, group 1 being the genes least tolerant of losing a copy. Missense variants: 479 observed, 487.06 expected, observed/expected ratio (o/e) 0.98, 90% interval 0.91 to 1.06. Synonymous variants: 178 observed, 192.79 expected, observed/expected ratio (o/e) 0.92, 90% interval 0.82 to 1.04.
Homologues: Orthologues: chimpanzee AADACL3 (98% identical), macaque AADACL3 (89% identical), pig AADACL3 (70% identical), dog AADACL3 (70% identical), rabbit AADACL3 (68% identical), guinea pig AADACL3 (62% identical), mouse Aadacl3 (62% identical), rat Aadacl3 (60% identical), Caenorhabditis elegans T09B9.1 (25% identical), Caenorhabditis elegans F16F9.4 (23% identical), Caenorhabditis elegans trcs-1 (23% identical), zebrafish si:dkey-193c22.1 (10% identical). Paralogues in human: AADACL4 (55% identical), AADAC (31% identical), AADACL2 (29% identical), NCEH1 (28% identical), AFMID (14% identical).
Diseases named in the same sentence as AADACL3 in open-access papers:
AADACL3 is named in the same sentence as 3 diseases in open-access papers, as found by Europe PMC text mining. Sharing a sentence is not in itself a finding about the gene and the disease.
AADACL3 shares sentences with these, for which no sentence is quoted: cancer (1 paper); neurodegenerative disease (1); Parkinson disease (1).